RNU6-107P (RNA, U6 small nuclear 107, pseudogene)
Gene: Small nuclear RNA gene on chromosome 2 (232,782,665 to 232,782,766, forward strand). Ensembl gene ENSG00000252452.
Homologues: Orthologues: chimpanzee U6 (99% identical), macaque U6 (76% identical). Paralogues in human: RNU6-1094P (81% identical), RNU6-41P (80% identical), RNU6-797P (80% identical), RNU6-1124P (79% identical), RNU6-1180P (79% identical), RNU6-11P (79% identical), RNU6-12P (79% identical), RNU6-1329P (79% identical), RNU6-13P (79% identical), RNU6-242P (79% identical), RNU6-25P (79% identical), RNU6-29P (79% identical), and 1284 more.